ABO (ABO, alpha 1-3-N-acetylgalactosaminyltransferase and alpha 1-3-galactosyltransferase)
Diseases named in the same sentence as ABO in open-access papers (continued):
Sharing a sentence is not in itself a finding about the gene and the disease.
COVID-19 (continued). "This study will add to the international pool of data on association of ABO-Rh blood types and COVID-19." (PMID 33437242, 2021). "We showed consistency of the association of ABO with the different COVID-19 phenotypes for both instrument selection strategies." (PMID 34402426, 2021). "At the same time, an association of the ABO blood group system with COVID-19 has also been highlighted: there is increasing evidence to suggest that non-O individuals are at higher risk of severe COVID-19 than O individuals." (PMID 33564039, 2021). "Our present finding, confirmed the relationship of ABO genetic system with susceptibility to COVID-19." (PMID 38624675, 2021). "We thus conducted this study based on the globally available big data to ascertain an association between the distribution of ABO blood types and the dynamics of the COVID-19 epidemic." (PMID 33407977, 2021). "Very recently, it has been reported that the prevalence and mortality of COVID-19 is associated with ABO (MIM: 616093) and Rh (MIM: 111680) blood groups, based on an ecologic study." (PMID 38624675, 2021). "All the SNPs that have showed an association signal are located at 3'-UTR, which play an important role in the ABO gene expression and transcriptional signaling in association with COVID-19 symptom presentation." (PMID 35096865, 2021). "This comprehensive, demographically unique study adds to the growing body of literature on this topic and furthers important insight into the association between ABO blood type and COVID-19." (PMID 34290882, 2021). "Following an initial study in Wuhan and Shenzhen in China, early in the coronavirus disease 2019 (COVID-19) pandemic, a large number of studies reported associations between ABO blood group and COVID-19." (PMID 35069504, 2021). "A study from China tested the association of ABO blood group with COVID-19 infection on 105 COVID-19 cases and 103 controls." (PMID 34905588, 2021). "Very recently, the ABO plasma protein levels have been associated with COVID-19 susceptibility and severity." (PMID 34972836, 2021). "There are several studies reporting the relationship of ABO and Rh blood groups with susceptibility to COVID-19 or with outcome of the COVID-19." (PMID 38624675, 2021). "This issue attracted us to determine the association between ABO/Rh-D blood types and COVID-19 in Peshawar, Pakistan where the ethnicity of the population is fairly homogenous." (PMID 33437242, 2021). "There are preliminary studies about the association between COVID-19 and ABO phenotypes and the results are controversial." (PMID 38624675, 2021). "Our studies of COVID-19 provide a test case for this and revealed possible mechanisms underlying the associations of severe COVID-19 with ABO and DPP9." (PMID 34001247, 2021). "Here, we investigated the relationship between the ABO blood type and the susceptibility to COVID-19." (PMID 34185186, 2021). "Recently, a newly published article in The New England Journal of Medicine presented a genetic piece of evidence that established a potential role of the ABO blood-group system as a risk factor for acquiring COVID-19." (PMID 33330542, 2020). "Growing evidence suggests that the ABO blood type contributed to the susceptibility of COVID-19, but the results are controversial." (PMID 32872048, 2020). "In the current study, we aimed to evaluate the contribution of the ABO blood group to COVID-19 susceptibility in Wuhan by employing a case-control association analysis." (PMID 32793517, 2020). "In line with these presentations, this study aimed to investigate the genetic association of ABO blood groups (A, B, AB and O) with risk of COVID-19 in Iraqi patients." (PMID 38624655, 2020). "We noticed that ABO blood groups exhibited various association risks for the infection with SARS-CoV-2 resulting in COVID-19." (PMID 33083341, 2020).
COVID-19 (continued). "The two ABO variants rs579459 (chr9:133278724, C>T) and rs495828 (chr9:133279294, T>G) have been investigated and shown to influence immunological response, potentially impacting the severity of COVID-19 and ensuing cardiovascular problems." (PMID 40002898, 2025). "Therefore, we aimed to explore the correlation between ABO blood group, Rh phenotype, MN blood group and susceptibility to COVID-19 based on the time sequence of infection during the pandemic." (PMID 38241306, 2024). "Earlier research has posited that the ABO gene, jointly associated with asthma and severe COVID-19, may partly explain the association between these conditions." (PMID 38750426, 2024). "Recent studies confirmed that the expression in the ABO gene locus (located in 9q34.2) of specific SNPs such as rs657152 and rs9411378 are respectively strongly and weakly associated to an increased risk of severe COVID-19." (PMID 36941580, 2023). "Finally, the rs48697960 SNP (CT genotype) within the fucosyltransferase 2 (FUT2) gene which regulates expression of the ABO blood group antigens is weakly correlated with increased risk of severe COVID-19 development." (PMID 36941580, 2023). "In 2020, it was hypothesized that the ABO blood group could be related to the predisposition to and severity of COVID-19." (PMID 37267401, 2023). "Surprisingly, we observed an opposite behaviour of blood groups after Omicron spread, with the O phenotype having a higher probability of infection than A. Since early works on SARS-CoV-2, the ABO group has been extensively investigated for its possible role in COVID-19 susceptibility." (PMID 37988390, 2023). "In addition to a suggestive association between CCL2-A2518G gene variants and the severity of COVID-19, a genome-wide study showed associations between the risk of severe COVID-19 and a multigene locus at 3p21.31 and the ABO blood group locus at 9q34.2." (PMID 37198402, 2023). "The ABO locus has also been revealed to be associated with COVID-19 severity." (PMID 36531218, 2022). "However, associations with the ABO locus, observed in many previous GWASs including a recent GWAS of severe coronavirus disease 2019 with respiratory failure, may also have arisen as a result of population stratification despite our best attempts to adjust for this." (PMID 34542150, 2022). "Akin to SARS-CoV-1, possible associations of the ABO blood groups with the severity of COVID-19 or different risks to become infected with SARS-CoV-2 have been discussed for a couple of months and have simultaneously gained a wide-spread interest in public media as well." (PMID 35364749, 2022). "Therefore, this study aims to explore COVID-19 vaccine side effects and its association with the ABO blood group among general surgeons in Saudi Arabia." (PMID 35494934, 2022). "Notably, we prioritized 34 risk genes, including potential causal genes of CXCR6, CCR1, and ABO, to be associated with severe COVID-19." (PMID 35172892, 2022). "Thus far, ten independent variants associated with COVID-19 severity at genome-wide significance have been identified, most notably at the ABO locus." (PMID 35482673, 2022). "Particularities of COVID-19 immunopathogenesis may depend on different host factors like age, gender, ABO blood group, and multiple risk factors." (PMID 35743779, 2022). "The PheWAS of ABO variants identified associations with increased risk of deep vein thrombosis, pulmonary embolism, and other circulatory disorders, in line with prior studies, and recent studies among patients hospitalized with COVID-19." (PMID 35482673, 2022). "Six ABO gene polymorphisms (rs651007 T/C, rs579459 T/C, rs495828 T/G, rs8176746 A/C, rs8176740 T/A, and rs512770 T/C) were determined using TaqMan genotyping assays in a group of 415 COVID-19 patients and 288 healthy controls." (PMID 35454075, 2022). "Therefore, the aim of this study was to evaluate the association between ABO rs657152 polymorphisms and ABO blood groups with COVID-19 mortality." (PMID 36419842, 2022).
COVID-19 (continued). "Besides comorbidities, genetic alterations in the ABO blood group system and variants of the 3p21.31 gene cluster have been linked to susceptibility to COVID-19 disease progression in adults." (PMID 34467455, 2022). "Furthermore, numerous recent reports have shown the association of ABO blood type with risk of COVID-19 illness." (PMID 37092112, 2022). "Variants of genes responsible for the SARS-CoV-2 entry pathway, host immune responses, and ABO blood groups, as well as being correlated with COVID-19, were analyzed to investigate the association between host genetic determinants and disease susceptibility and severity." (PMID 36292769, 2022). "In particular, group A was linked to death while group O was at low risk of infection, suggesting that ABO antigens may have a notable role in the pathogenesis of COVID-19." (PMID 35419105, 2022). "However, we identified several blood markers robustly associated with COVID-19, including ABO, suggesting that our SNP instruments pick up true associations and potential underlying biology of COVID-19." (PMID 35239653, 2022). "Hence, we performed ABO typing on 373 Saudi patients infected with SARS-CoV-2 to explore the relationship between ABO blood group phenotypes and COVID-19 susceptibility and severity." (PMID 34978705, 2022). "Therefore, even though previous studies are in line with our preliminary results, more individuals should be analyzed before concluding about ABO-associated antibodies and the severity of COVID-19 symptoms." (PMID 34967260, 2022). "In this study, the ABO rs657152 AA genotype had a strong association with COVID-19 mortality." (PMID 36419842, 2022). "To date, a meta-analysis illustrates that the association between the ABO blood group and the infection of COVID-19 is that blood type A might be more susceptible to infecting COVID-19, while blood type O might be less susceptible to infecting COVID-19." (PMID 35923409, 2022). "We conducted a case-control study in order to evaluate whether ABO gene polymorphisms were associated with a high risk of developing COVID-19 in a cohort of patients." (PMID 35454075, 2022). "The ABO gene within the 9q34.2 locus was implicated in both asthma and COVID-19." (PMID 35386719, 2022). "In this study, even with the adjustment of stratification for ancestry, 8 SNPs were identified on the ABO gene locus to be significantly associated with COVID-19 severity, with a lower frequency (protective factor) of the effect allele in patients with blood group O." (PMID 35096865, 2021). "Therefore, further investigation and study are warranted to clarify the relationship between COVID-19 and the ABO gene variants, especially with respect to regional differences." (PMID 35096865, 2021). "Multiple studies have now reported the association of the ABO locus with risk of COVID-19." (PMID 34001247, 2021). "The ABO polymorphism is known to associate with some of these COVID-19 risk factors, which might explain the link between blood group O and a lesser risk of COVID-19." (PMID 33499228, 2021). "For example, association with VWF and Factor VIII may indicate ABO affects COVID-19 through regulation of thrombosis, as patients with severe COVID-19 can have thromboembolic complications as part of a hyper-inflammatory state." (PMID 34001247, 2021). "In conclusion, we integrated genetic investigation with functional assessments of CD209, a receptor in moDCs, and postulated that this target may convey the COVID-19 risk of the ABO signal." (PMID 34402426, 2021). "Soon after the first report of an association between ABO phenotypes and the risk of COVID-19, several hypotheses were proposed about the underlying mechanisms." (PMID 33499228, 2021). "It is controversial whether the association of the ABO system with COVID-19 could be attributable to the amount of A- or B-antigens on cells or anti-A or -B antibodies in serum." (PMID 33564039, 2021).
COVID-19 (continued). "Thus, although no intrinsic differences in susceptibility according to ABO blood type were detected, ABO incompatibility strongly decreased the risk of COVID-19 transmission, suggesting that anti-ABO antibodies contribute to virus neutralization." (PMID 35069504, 2021). "Therefore, we investigated the association of ABO and Rh blood group with COVID-19 susceptibility, prognosis, recovery time, and mortality in this study." (PMID 34796130, 2021). "Variants with inverse correlation with COVID-19 cases include a variant in ABO which increases the expression of its transcript, and the two unrelated variants in ACE2 which may potentially increase the expression of PIR mRNA in both lung and blood." (PMID 33981715, 2021). "Most interestingly, the ABO locus is associated with both COVID-19 and CD209 (p = 0.008)." (PMID 34001247, 2021). "Therefore, the present case-control study was performed to determine the association of COVID-19 with ABO blood groups considering the Rh blood groups simultaneously." (PMID 38624675, 2021). "Furthermore, several investigations have investigated an association of ABO blood group with COVID-19." (PMID 34905588, 2021). "Taken together, these findings suggest that the ABO system could be another druggable target for alleviation of COVID-19 risk, i.e. reduction of A- and B-antigens might reduce the risks of COVID-19." (PMID 33564039, 2021). "Furthermore, a study with 2,173 patients from different Chinese hospitals reported that ABO blood groups display different association risks for the infection with SARS-CoV-2 resulting in COVID-19." (PMID 35178379, 2021). "Another region previously associated with COVID-19 was the blood group ABO locus at 9q34.2." (PMID 34557504, 2021). "However, studies on the association between COVID-19 and ABO phenotypes are at preliminary stage and the results are controversial." (PMID 38624675, 2021). "Genetic variations in ABO are an established risk factor for COVID-19 severity." (PMID 34642702, 2021). "In this study we found evidence for associations between ABO and Rh blood groups and COVID-19." (PMID 32511586, 2020). "Association analysis of ABO blood type between COVID-19 cases and controls." (PMID 32793517, 2020). "Additionally, non-coding variants within the ABO locus have been reported to be associated with COVID-19 severity, VWF levels, VTE risk, and a spectrum of hematological, cardiovascular, and metabolic traits, in some cases across distinct studies and phenotypic analyses." (PMID 41311061, 2025). "The first genome-wide association study (GWAS) of COVID-19 (Severe COVID-19 GWAS Group Study) identified two loci associated with disease severity in Italians and Spaniards: the 3p21.31 loci, which contains several immune genes, and the ABO locus, which determines ABO blood groups." (PMID 40573382, 2025). "Furthermore, ABO blood group phenotypes have been correlated with the risk of developing COVID-19." (PMID 38792740, 2024). "Concerning the 9q34.2 locus, it harbors the ABO, alpha 1-3-N-acetylgalactosaminyltransferase and alpha 1-3-galactosyltransferase (ABO) gene, which may modulate COVID-19 susceptibility and symptom severity through immunological interactions and inflammatory responses." (PMID 38750426, 2024). "In addition to ABO blood type, receptors, and immune genes, GWAS studies on COVID-19 have revealed the association of SLC6A20 (rs2271616), LZTFL1 (rs10490770, rs11385942, rs73064425), and DPP9 (rs2109069) genes with respiratory failure caused by COVID-19 infection and critical illness." (PMID 36292769, 2022). "Therefore, the association between ABO variants with fibrinogen may suggest that ABO influences COVID-19 via regulating thrombosis, which provided a functional explanation for the observed association of ABO with COVID-19 risk." (PMID 35736459, 2022).
COVID-19 (continued). "Thus, iCPAGdb and subsequent colocalization analysis support a model where ABO regulates CD209 protein levels to impact COVID-19 risk, though much future experimental and clinical studies will be required to fully test this hypothesis." (PMID 34001247, 2021). "Using the set of identified ABO-associated genetic variants as instrumental variables, we demonstrate the application in causal analysis by Mendelian randomization (MR) studies on blood pressures (one-sample MR) and severe COVID-19 with respiratory failure (two-sample MR)." (PMID 34202464, 2021). "However, divergent results are still coming forth with respect to the role of the ABO blood groups as a risk marker for COVID-19 severity linked to possible comorbidities and methodological differences as well as population differences in tissue receptors associated with SARS-CoV-2 infection." (PMID 35096865, 2021). "To test whether an association exists between ABO phenotype and COVID-19 severity in our San Diego County study population, we conducted a large, retrospective review of patients hospitalized for COVID-19, factoring in relevant demographic and clinical confounders." (PMID 34290882, 2021). "For instance, one study of COVID-19 patients who experienced respiratory failure at seven hospitals in Italy and Spain found a fairly strong association in a cluster of genes lying on part of chromosome 3 and a borderline association in chromosome 9 encompassing the ABO blood group locus." (PMID 33036646, 2020). "However, ABO blood groups have been recently introduced as a genetic system that may influence susceptibility to COVID-19." (PMID 38624532, 2020). "The results of these genetic factors in the genes (TLR7, UNC13D, DES, SPEG, LZTFL1, ABO, ILRUN, and CACFD1) provide substantial insights into the genesis of cardiovascular issues linked with COVID-19." (PMID 40002898, 2025). "Our chromatin conformation analyses provide evidence that non-coding variants in ABO, associated with VWF levels, VTE risk, and COVID-19 severity, are in spatial proximity to ADAMTS13 in endothelial cells." (PMID 41311061, 2025). "From the GWAS Catalog, at the ABO locus, we have identified a total of 26 variants related to VWF levels, 29 variants related to VTE, and 43 variants related to COVID-19 (A1–A3)." (PMID 41311061, 2025). "Of the 128 participants, 25 were included in our previous report examining the relationships between ABO and severity of COVID-19." (PMID 40173171, 2025). "A recent study developed by our research group investigated genetic variants present in the genes SLC6A20, LZTFL1, CCR9, FYCO1, CXCR6, XR1 and ABO involved with the severity of COVID-19 in indigenous people." (PMID 38543725, 2024). "The ABO blood group and Rh factor distribution in health care providers (HCWs), according to the presence of anti-COVID-19 antibodies in their serum samples." (PMID 39413075, 2024). "This comprehensive narrative review aimed to explore the literature and to present the current state of knowledge on reported associations of the ABO, Lewis, and secretor blood groups with SARS-CoV-2 infection and COVID-19 severity." (PMID 38672973, 2024). "Adjusted for confounding factors, including COVID-19 exposure during the MGEs, attack rates of COVID-19 for each ABO group were 55.4%, 59.6%, 60.2%, and 63.7%." (PMID 36810454, 2023). "Suggestively, several genome-wide association studies (GWASs) identified certain SNPs responsible for COVID-19 susceptibility, including ACE2 and ABO, which were also found to be associated with CHD risks." (PMID 37964352, 2023). "In COVID-19 patients, ABO contributes to hypercoagulation states and thromboses by affecting plasma glycoproteins, meanwhile, such hypercoagulation states also frequently occurs in many cancer patients." (PMID 37636041, 2023). "As in S1 Table, those patients admitted with COVID-19 whose ABO blood group was determined were significantly older and had more severe disease overall." (PMID 37267401, 2023).